PPP1R17 (protein phosphatase 1 regulatory subunit 17)
Description:
Inhibits phosphatase activities of protein phosphatase 1 (PP1) and protein phosphatase 2A (PP2A) complexes.
Synonyms: C7orf16; GSBS
Tractability: PROTAC: ubiquitination databases record sites on it.
Gene: Protein-coding gene on chromosome 7 (31,687,215 to 31,708,457, forward strand). Ensembl gene ENSG00000106341.
Gene Ontology:
Molecular function: protein serine/threonine phosphatase inhibitor activity; phosphatase inhibitor activity; protein phosphatase inhibitor activity
Biological process: central nervous system development; intracellular signal transduction; regulation of phosphatase activity
Genetic constraint (gnomAD): Loss-of-function variants: 12 observed, 14.81 expected, observed/expected ratio (o/e) 0.81, 90% interval 0.52 to 1.31. The upper end of that interval is the gene's LOEUF score, 1.31, which puts it in group 5 of 6, group 1 being the genes least tolerant of losing a copy. Missense variants: 196 observed, 184.29 expected, observed/expected ratio (o/e) 1.06, 90% interval 0.95 to 1.2. Synonymous variants: 63 observed, 63.89 expected, observed/expected ratio (o/e) 0.99, 90% interval 0.8 to 1.22.
Homologues: Orthologues: chimpanzee PPP1R17 (100% identical), macaque PPP1R17 (98% identical), dog PPP1R17 (87% identical), guinea pig PPP1R17 (86% identical), rabbit PPP1R17 (84% identical), rat Ppp1r17 (81% identical), mouse Ppp1r17 (80% identical), tropical clawed frog ppp1r17 (46% identical).
Diseases named in the same sentence as PPP1R17 in open-access papers:
PPP1R17 is named in the same sentence as 12 diseases in open-access papers, as found by Europe PMC text mining. Sharing a sentence is not in itself a finding about the gene and the disease. The quoted sentences say what the papers report.
adenoma (1 paper, 2025). A neoplasm arising from the epithelium. "Mechanistically,PPP1R17overexpression in normal murine pituitary cells recapitulated the adenoma phenotype, and PPP1R17-mediated tumorigenesis was reversible using an FDA-approved small molecule PP2A agonist both in-vitro and in-vivo." (PMID 41473325, 2025).
Anxiety (1 paper, 2021). Intense feelings of nervousness, tension, or panic often arise in response to interpersonal stresses. "Ppp1r17 and Grid2 have not been studied in the context of anxiety." (PMID 34276303, 2021).
depression (1 paper, 2021). "In the restrained group, genes involved in long-term depression (Plcb4, Gucy1a3, Prkg2, Ppp1r17, Grid2, and Crhr1) were downregulated compared to the control group." (PMID 34276303, 2021).
Hypercholesterolemia (1 paper, 2018). An increased concentration of cholesterol in the blood. "PPP1r17 is reportedly involved in hypercholesterolemia, long‐term depression, and attenuation in the long‐term adaptation of optokinetic eye movement response." (PMID 29943428, 2018).
lung carcinoma (1 paper, 2023). "PPP1R17 is a member of an open reading frame that has been found to be associated with multiple solid tumors, including colorectal and lung cancer." (PMID 37023088, 2023).
neuroblastoma (1 paper, 2025). Neuroblastoma (NB) is the most common solid, extracranial childhood tumor. "Compared to baseline control values, NEUROG2 elevated luciferase activity in SHSY-5Y human neuroblastoma cells using either the PPP1R17-HAR or -TSS reporters." (PMID 39680368, 2025).
Obesity (1 paper, 2021). Accumulation of substantial excess body fat. "In addition to its basic science importance, these findings could have therapeutic applications, as they suggest that pharmacologic activation of PPP1R17 neurons could potentially reduce weight in settings of obesity and binge-like eating." (PMID 33753517, 2021).
tumor (2 papers, 2023 to 2025). "We identified six cell types, including macrophages (PPP1R17), monocytes and neutrophils (FCAR, S100A12, CD93), tumor stem cells (CPZ), smooth muscle cell populations and epithelial cells (CSF3, TTC23L)." (PMID 41049004, 2025).
PPP1R17 also shares sentences with these, for which no sentence is quoted: atherosclerosis (1 paper); cancer (1); metabolic disease (1); viral infection (1).